DSCAM (DS cell adhesion molecule)
Diseases named in the same sentence as DSCAM in open-access papers (continued):
Sharing a sentence is not in itself a finding about the gene and the disease.
Anxiety (3 papers, 2019 to 2024). Intense feelings of nervousness, tension, or panic often arise in response to interpersonal stresses. "First, loss of one copy of DSCAM led to a significant increase in activity and anxiety‐like behavior when exploring a novel environment." (PMID 39294095, 2024). "SNPs in the DSCAM gene have also been associated with idiopathic scoliosis in adolescents and with anxiety and depression disorder." (PMID 30901340, 2019). "Here, we conducted a comprehensive cognitive behavioral phenotyping which revealed that loss of one copy of DSCAM, as in the DSCAM2J+/−, that is, DSCAM heterozygous mice, displayed hyperactivity, increased anxiety‐like behavior, and motor coordination deficits." (PMID 39294095, 2024). "In the EPM, the NEX-Dscam f/f mice entered open and closed arms at similar rates as the control mice did, but they reduced the duration spent in open arms, suggesting that DSCAM deficiency in pyramidal neurons does not induce anxiety-like behaviors." (PMID 34848499, 2022).
autism spectrum disorder (3 papers, 2021 to 2025). A spectrum of developmental disorders that includes autism, and Asperger syndrome. "Similarly, DSCAM loss-of-function mutations show a relatively high frequency in autism spectrum disorder (ASD) patients, and Dscam deficiency leads to abnormal voluntary locomotor control and ASD-like behaviors in mouse models." (PMID 40385132, 2025). "Also, altered function in the DSCAM gene has been related to autism spectrum disorders and other neurological alterations." (PMID 41374081, 2025).
scoliosis (3 papers, 2021 to 2025). A congenital or acquired spinal deformity characterized by lateral curvature of the spine. "Several genes encoding commissural axon guidance molecules, including ROBO3, EPHA4, CHL1, and DSCAM, are strongly associated with scoliosis." (PMID 37962965, 2024). "This identified 12 CNVs in four scoliosis-associated genes (TBX6, NOTCH2, DSCAM, and SNTG1) as well as eight recessive and 64 novel rare CNVs in 15 additional genes." (PMID 34440387, 2021).
Alzheimer disease (2 papers, 2024 to 2025). A progressive, neurodegenerative disease characterized by loss of function and death of nerve cells in several areas of the brain leading to loss of cognitive function such as memory and language. "Furthermore, recent studies put forward that DSCAM might be one of the key molecules involved in neuronal age-related mechanisms during early stage of Alzheimer’s disease (AD), a neurodegenerative disease linked to aberrant homeostatic mechanisms." (PMID 40385132, 2025).
cardiomyopathies (2 papers, 2011 to 2014). "Grossman and colleagues studied the effect of the coexpression of DSCAM and COL6A2, interaction partners that are overexpressed in DS patients and are associated with cardiomyopathy." (PMID 25478570, 2014).
cognitive decline (2 papers, 2017 to 2025). "The protein DSCAM (Down syndrome cell adhesion molecule that belongs to the immunoglobulin superfamily) is involved in synaptic function and in neuronal development, which may affect cognitive decline." (PMID 40748434, 2025).
Bicuspid aortic valve (1 paper, 2024). The presence of an aortic valve with two instead of the normal three cusps (flaps). "Additionally, copy number duplications encompassing DSCAM were identified in patients with unexplained bicuspid aortic valve and other CHDs." (PMID 38828726, 2024).
breast carcinoma (1 paper, 2018). "On the contrary, low levels of the coding DSCAM transcript are detectable in breast cancer cells and no function of DSCAM in mammary tissues has been described to date." (PMID 29462945, 2018).
breast tumors (1 paper, 2013). "DSCAM was affected by complex SVs including amplification, inversion, deletion and interchromosomal translocation in three additional breast tumors." (PMID 23496902, 2013).
cardiac hypertrophy (1 paper, 2011). "Cooperative interactions between DSCAM and COL6A2 were also observed in the H9C2 cardiac cell line and transcriptional analysis of this interaction points to genes involved in adhesion and cardiac hypertrophy." (PMID 22072978, 2011). "Further analysis will be required to determine whether DSCAM and COL6A2 contribute to ASD typical of DS and whether levels of these two genes are jointly increased in patients with inherited or spontaneous forms of cardiac hypertrophy." (PMID 22072978, 2011).
colon cancer (1 paper, 2024). "Analysis of the TCGA database revealed a significant decrease in PTPRD expression in colon cancer, while DSCAM showed a significant decrease in rectal cancer (PTPRD: p = 1.500E-02; DSCAM: p = 4.556E-02)." (PMID 39639918, 2024). "Expression analysis showed that PTPRD decreased in colon cancer and DSCAM decreased in rectal cancer." (PMID 39639918, 2024).
endometrioid endometrial adenocarcinoma (1 paper, 2025). "DSCAM was hypermethylated in UCEC and was associated with the histologic type, with the highest degree of methylation in the endometrioid endometrial adenocarcinoma." (PMID 41407823, 2025).
esophageal cancer (1 paper, 2017). A primary or metastatic malignant neoplasm involving the esophagus. "We identified a DSCAM mutation not previously reported in cancer (Gly1679Ser; human: Gly1915Ser) and an Arg1562* mutation, whose human homologue, Arg1798*, has been identified in esophageal cancer." (PMID 29190660, 2017).
fungal infections (1 paper, 2019). "DSCAM’s immune priming to viruses has been previously validated, however, studies of DSCAM functioning in response to bacterial and fungal infections remain insufficient." (PMID 31372182, 2019).
heart failure (1 paper, 2011). Inability of the heart to pump blood at an adequate rate to meet tissue metabolic requirements. "As an example of a cooperative effect, expression of either DSCAM or COL6A2 alone resulted in ≈35% heart failure rate (N = 200 for each genotype), but when these two genes were co-expressed, the failure rate nearly doubled to 60% (N = 200; p<0.05)." (PMID 22072978, 2011).
leukemia (1 paper, 2010). A malignant (clonal) hematologic disorder, involving hematopoietic stem cells and characterized by the presence of primitive or atypical myeloid or lymphoid cells in the bone marrow and the blood. "The application on a dataset of leukemia patients identifies eQTLs in the regions of the GART, PCP4, DSCAM, and RIPK4 genes that regulate ADAMTS1, a known leukemia correlate." (PMID 21044360, 2010).
lung carcinoma (1 paper, 2023). "Some known lung cancer susceptibility loci were also showed association with trajectory scores, such as NPAS3 locus (rs7154051, significant level P = 1.19e-07), DSCAM locus (rs1569094034, significant level P = 5.54e-07) and VLDLR-AS1 locus (rs7029746, significant level P = 1.15e-06)." (PMID 37228122, 2023).
mast cell tumours (1 paper, 2019). "Using a methodological approach that combined a genome-wide association study, targeted next generation sequencing, and TaqMan genotyping, we identified a synonymous variant in the DSCAM gene on canine chromosome 31 that is associated with mast cell tumours in Labrador Retrievers." (PMID 30901340, 2019).
melanoma (1 paper, 2024). A malignant, usually aggressive tumor composed of atypical, neoplastic melanocytes. "The most frequently mutated genes in human melanoma were those mutated in parental and dormant mouse cells (common genes), with up to 80% mutation rates for TTN, followed by PCLO (> 52%), DSCAM (approximately 40%), and OBSCN (approximately 34%)." (PMID 39223638, 2024).
ovarian carcinoma (1 paper, 2020). A malignant neoplasm originating from the surface ovarian epithelium. "Down Syndrome Cell Adhesion Molecule (DSCAM) antisense (DSCAM-AS1), (DSCAM-AS1), a novel lncRNA, has been reported to be upregulated and function as oncogenic lncRNA in hepatocellular carcinoma, non-small lung cancer, ovarian cancer, melanoma and breast cancer." (PMID 32453706, 2020).
renal carcinoma (1 paper, 2025). A carcinoma arising from the epithelium of the renal parenchyma or the renal pelvis. "In general, NTN1, NEO1, DSCAM, UNC5C, and UNC5D are all regulated by HDAC members in renal cancer, suggesting that NTN1, NEO1, DSCAM, UNC5C, UNC5D, and especially NEO1 and UNC5C may be essential for the regulation and outcome of renal cancer." (PMID 41407823, 2025).
Tetralogy of Fallot (1 paper, 2006). A congenital cardiac malformation comprising pulmonary stenosis, overriding aorta, ventricular septum defect, and right ventricular hypertrophy. "The other important approach, genetic mapping using partial trisomies in humans, has led to evidence that the DSCAM gene may be in a critical region for Tetralogy of Fallot." (PMID 16539728, 2006).
cancer (8 papers, 2017 to 2025). A tumor composed of atypical neoplastic, often pleomorphic cells that invade other tissues. "Three patients had mutations in eight genes, of which TCGA-A5-A0G1-01 had mutations in genes except for DSCAM; and all cancers were UCEC." (PMID 41407823, 2025). "However, one of the hot spot mutations in DSCAM, E368K, occurred in seven patients with two cancers (SKCM, UCEC) and was damaged in both VEST3 and REVEL algorithms." (PMID 41407823, 2025). "We found that NTN1, DCC, DSCAM, MCAM, and UNC5D were methylated in many cancers, of which UNC5D was the most prominent." (PMID 41407823, 2025). "Netrin-1 regulates axon guidance as both attractive and repulsive cues by binding to Unc5 family proteins, deleted in colorectal carcinoma (DCC), neogenin, down syndrome cell adhesion molecule (DSCAM), and integrin family proteins in vertebrates." (PMID 33324143, 2020). "For instance, netrin-1, a classic bifunctional guidance cue, is capable of attracting or repelling axon projection by differentially interacting with its receptors, deleted in colorectal cancer (DCC), neogenin, uncoordinated-5 (UNC5), and Down syndrome cell adhesion molecule (DSCAM)." (PMID 31226147, 2019).
tumor (4 papers, 2019 to 2025). "Overexpression of DSCAM and ADORA2A in HNC has been correlated with tumor progression and a poorer prognosis, thereby identifying them as potential therapeutic targets." (PMID 39628997, 2024). "Furthermore, these two cases shared a common five-member mutant cell surface receptor signature as well (DSCAM, IGSF21, GHR, GRINA2 and RP1), suggesting that they may also have been involved in the massive antitumoral response to the primary tumor." (PMID 36980598, 2023).
infection (3 papers, 2009 to 2025). The state of being infected such as from the introduction of a foreign agent such as serum, vaccine, antigenic substance or organism. "Genes involved in cellular signaling (e.g., G-protein coupled receptors, Spaetzle 5, DSCAM) and transcriptional regulation (i.e., changing patterns in transcription factors) were identified as components of the infection response at this time interval." (PMID 19823571, 2009). "Recognizing a pathogen and producing preselected, pathogen-binding DSCAM forms could potentially eliminate the infection in its early stages." (PMID 40591395, 2025). "Additionally, RNA-Seq showed that PRV inoculation during the early stage of infection led to an increase in the transcription/expression of several cellular receptors [e.g., ICAM5, ICAM2, ACAN, and DSCAM] that are known to facilitate bacterial adherence." (PMID 39041808, 2024).
neurological diseases (3 papers, 2022 to 2023). "The dose-dependent function of DSCAM suggests that dysregulated DSCAM levels may be a common pathogenic driver of GABAergic dysfunctions related to neurological diseases." (PMID 37079499, 2023). "Therefore, dysregulated DSCAM expression levels may be a common contributor to GABAergic dysfunctions in associated neurological diseases." (PMID 37079499, 2023). "By consulting relevant literature, 6 genes related to neurodevelopmental and neurological diseases (GPC5, CA10, DSCAM, IL1RAPL2, CNTN2, and SPOCK3) were verified by ELISA method." (PMID 37539343, 2023). "Finally, six genes/proteins related to neurodevelopmental and neurological diseases (GPC5, CA10, DSCAM, IL1RAPL2, CNTN2, and SPOCK3) were verified by ELISA." (PMID 37539343, 2023).
bacterial infection (2 papers, 2016 to 2025). "However, both circulating and membrane-bound forms of DSCAM are necessary for combating bacterial infections." (PMID 40591395, 2025).
brain disorder (1 paper, 2023). A disease affecting the brain or part of the brain. "Although recent findings suggest a conserved role of DSCAM in promoting presynaptic growth in vertebrates, whether dysregulated DSCAM expression results in neuronal defects in brain disorders remains to be empirically determined." (PMID 37079499, 2023). "As a control, normalizing DSCAM gene dosage did not change the increased level of amyloid precursor protein (APP) in Ts65Dn, which is encoded by another HSA21 gene that is important for brain disorders of DS." (PMID 37079499, 2023).
DSCAM also shares sentences with these, for which no sentence is quoted: congenital heart defects (4 papers); fragile X syndrome (3); neurodevelopmental disorder (3); pancreatic cancer (2); renal cell carcinoma (2); 22q11.2 deletion syndrome (1); amyotrophic lateral sclerosis (1); autoimmune disease (1); Chagas disease (1); depression disorder (1); endometrial cancer (1); endothelial dysfunction (1); epilepsy (1); heart disease (1); holoprosencephaly (1); Hypertension (1); hypertrophic cardiomyopathy (1); idiopathic scoliosis (1); metastatic disease (1); neurodegenerative disease (1); non-small cell lung carcinoma (1); Nystagmus (1); Parkinson disease (1); prostate carcinoma (1); rectal cancer (1); skin melanoma (1); uveal melanoma (1).